LGI1 (leucine rich glioma inactivated 1)
Description:
Regulates voltage-gated potassium channels assembled from KCNA1, KCNA4 and KCNAB1. It slows down channel inactivation by precluding channel closure mediated by the KCNAB1 subunit. Ligand for ADAM22 that positively regulates synaptic transmission mediated by AMPA-type glutamate receptors (By similarity). Plays a role in suppressing the production of MMP1/3 through the phosphatidylinositol 3-kinase/ERK pathway.
Synonyms: EPT; IB1099; ETL1; EPITEMPIN; ADLTE; ADPAEF; ADPEAF; DEE121
Tractability: Antibody: UniProt places it where antibodies can reach, with high confidence; its Gene Ontology location is reachable by antibodies, with high confidence; UniProt predicts a signal peptide or a membrane-spanning region. PROTAC: ubiquitination databases record sites on it; its protein half-life has been measured.
Gene: Protein-coding gene on chromosome 10 (93,757,840 to 93,806,272, forward strand). Ensembl gene ENSG00000108231.
Subcellular location: Secreted; Synapse; Cytoplasm; Golgi apparatus (Isoform 1); Endoplasmic reticulum (Isoform 2)
Pathways (Reactome):
Developmental Biology: LGI-ADAM interactions
Gene Ontology:
Molecular function: protein binding; signaling receptor binding; receptor ligand activity
Biological process: axon guidance; neuron projection development; positive regulation of cell growth; regulation of AMPA receptor activity; negative regulation of voltage-gated potassium channel activity; nervous system development; positive regulation of synaptic transmission; regulation of AMPA glutamate receptor clustering; regulation of synapse assembly; neurotransmitter receptor localization to postsynaptic specialization membrane; signal transduction
Cellular component: endoplasmic reticulum; extracellular region; Golgi apparatus; trans-synaptic protein complex; cytoplasm; non-collagenous component of interstitial matrix; synapse; axon initial segment; dendrite; glutamatergic synapse; synaptic cleft
Genetic constraint (gnomAD): Loss-of-function variants: 10 observed, 51.39 expected, observed/expected ratio (o/e) 0.19, 90% interval 0.12 to 0.33. The upper end of that interval is the gene's LOEUF score, 0.33, which puts it in group 1 of 6, group 1 being the genes least tolerant of losing a copy. Missense variants: 402 observed, 644.23 expected, observed/expected ratio (o/e) 0.62, 90% interval 0.57 to 0.68. Synonymous variants: 205 observed, 235.38 expected, observed/expected ratio (o/e) 0.87, 90% interval 0.78 to 0.98.
Gene-disease validity (ClinGen):
ClinGen rates the evidence that LGI1 causes each of these diseases.
autosomal dominant epilepsy with auditory features (autosomal dominant): Definitive. A rare, genetic, familial partial epilepsy disease characterized by focal seizures associated with prominent ictal auditory symptoms, and/or receptive aphasia, presenting in two or more family members and having a relatively benign evolution.
Homologues: Orthologues: macaque LGI1 (100% identical), chimpanzee LGI1 (99% identical), dog LGI1 (99% identical), rabbit LGI1 (99% identical), pig LGI1 (98% identical), guinea pig LGI1 (98% identical), mouse Lgi1 (97% identical), rat Lgi1 (97% identical), tropical clawed frog lgi1 (80% identical), zebrafish lgi1b (68% identical), zebrafish lgi1a (63% identical), Drosophila melanogaster kek3 (19% identical), and 7 more. Paralogues in human: LGI2 (54% identical), LGI3 (51% identical), LGI4 (47% identical), LGR5 (19% identical), LGR6 (19% identical), LRIG1 (18% identical), LRIG3 (18% identical), LRIG2 (17% identical), LGR4 (17% identical), ELFN2 (15% identical), ELFN1 (15% identical), LRIT3 (13% identical), and 10 more.
Diseases named in the same sentence as LGI1 in open-access papers:
LGI1 is named in the same sentence as 202 diseases in open-access papers, as found by Europe PMC text mining. Sharing a sentence is not in itself a finding about the gene and the disease. The quoted sentences say what the papers report.
encephalitis (335 papers, 2013 to 2026). An acute inflammatory process affecting the brain parenchyma. "Acute hippocampal swelling is associated with worse outcomes in anti-LGI1 Ab-mediated encephalitis and, alongside initial T2/FLAIR hyperintensity, is associated with the development of both mesial temporal atrophy and hippocampal sclerosis." (PMID 42318510, 2026). "Anti-leucine-rich glioma-inactivated protein 1 (anti-LGI1) encephalitis is an autoimmune encephalitis caused by autoantibodies against LGI1 and often presents with subacute cognitive decline, behavioral symptoms, and seizures." (PMID 41164023, 2025). "Sleep disturbances are often frequent and severe, particularly in anti-NMDA, anti-LGI1 and anti-IgLON5 encephalitis, and the associated fatigue is an accurate predictor of poor long-term QoL." (PMID 40514744, 2025). "The results of the study indicated that DRB1*03:01 or DQB1*02:01 allele and the extended DRB1*03:01 ~ DQB1*02:01 haplotype represented strong susceptibility loci for anti-LGI1 encephalitis." (PMID 39820999, 2025). "This complex pattern of metabolic covariance across multiple regions likely reflects widespread inflammatory involvement in anti‐LGI1 encephalitis and underlies regional functional impairments." (PMID 41399525, 2025). "The clinical presentation of LGI-1 antibody-associated encephalitis is heterogeneous, often leading to misdiagnosis as other neurological or psychiatric disorders." (PMID 40904981, 2025). "DRB1*07 has been suggested as a risk allele for juvenile myoclonic epilepsy, and both DRB4 and DRB1*07 have been associated with anti-LGI1 encephalitis." (PMID 40565278, 2025). "The anti-LGI1-antibody-associated encephalitis is another prevalent AE syndrome that affects limbic temporal lobe areas leading to severe permanent deficits in anterograde and episodic memory functions in up to one-third of patients." (PMID 40895099, 2025). "The neurological findings and anti-LGI1 antibody profiles at the relapse did not converge on the typical constellation of diagnostic signatures of anti-LGI1 encephalitis." (PMID 41164023, 2025). "Anti-LGI1 (leucine-rich glioma-inactivated protein 1) antibody-associated encephalitis is a rare autoimmune disorder affecting the brain but is considered the most common cause of autoimmune encephalitis in adults older than 40 years with male predominance." (PMID 41311428, 2025). "Genetic predisposition also plays a role, as anti-LGI1 encephalitis is linked to the DRB107:01-DQB102:02 haplotype in HLA class II and B*44:03 in HLA class I." (PMID 41311428, 2025). "The direct costs associated with anti-LGI1/CASPR2 encephalitis were notably lower than those linked with anti-NMDAR encephalitis and anti-GABAR encephalitis." (PMID 39820999, 2025). "In terms of CSF characteristics, anti-LGI1 antibody–associated encephalitis typically shows only mild inflammatory changes." (PMID 41473232, 2025). "Older age, MRI T2/FLAIR hyperintensity, RSE and first-line immunotherapy failure predicted worse mRS and composite clinical-functional outcome at 12 months, while a diagnosis of anti-LGI1 antibody-mediated encephalitis was associated with favourable outcomes." (PMID 40281286, 2025). "Paraclinical findings, such as brain MRI findings or LGI1 antibody titers in CSF or serum, are generally considered diagnostic biomarkers in anti-LGI1 encephalitis." (PMID 41164023, 2025). "Further research is warranted to clarify the hypothalamic mechanisms underlying hyponatremia in anti‐LGI1 encephalitis." (PMID 41399525, 2025). "In one of these cases, the causal relationship between LGI1 encephalitis and a squamous lung cancer was supported by the finding that the tumor strongly expressed the LGI1 antigen." (PMID 40407616, 2025). "Epidemiological data suggest that anti-LGI1 antibody-associated encephalitis predominantly affects middle-aged and elderly individuals." (PMID 41473232, 2025).
encephalitis (continued). "Anti-LGI1 encephalitis is strongly associated with the DRB1*07:01-DQB1*02:02 haplotype, as well as with the DRB1*03:01 allele." (PMID 39820999, 2025). "Younger age and anti-LGI1 Ab-mediated encephalitis were associated with better outcomes at 12 months, and RSE, acute T2/FLAIR hyperintensity on MRI, first-line immunotherapy failure and a diagnosis of definite AILE were associated with worse outcomes." (PMID 40281286, 2025). "Second, because diagnostic biomarkers in anti-LGI1 encephalitis, such as increased antibody titers or apparent worsening of the medial temporal lobe MRI lesions, are sometimes absent in relapse." (PMID 41164023, 2025). "Anti-LGI1 encephalitis has classically been associated with cognitive changes, faciobrachial spasms/seizures and hyponatremia which is usually present in 60–70% of patients due to autoantibody-binding to LGI1-expressing, ADH-secreting neurons." (PMID 41311428, 2025). "Of all the enrolled patients, 47 patients fulfilled diagnostic criteria for acute anti‐LGI1 encephalitis; three of them also underwent follow‐up 18F‐FDG PET/CT in the remission phase." (PMID 41399525, 2025). "first reported anti-LGI1 antibody-associated encephalitis in 2010 and identified anti-LGI1 as the causative antibody." (PMID 40519939, 2025). "DRB1*07:01 in particular has been suggested as a risk for juvenile myoclonic epilepsy, and both DRB4 and DRB1*07 have been associated with anti-LGI1 encephalitis." (PMID 40565278, 2025). "It is, therefore, plausible that these pathomechanisms underlie the remediable aspects of anti-LGI1 encephalitis." (PMID 39105896, 2024). "For anti-LGI1 encephalitis, poor long-term outcomes are associated with ineffective initial treatment and relapse, with factors like advanced age and abnormal cerebrospinal fluid also contributing." (PMID 39539648, 2024). "More studies are needed to better understand the underlying cause of seizures in anti-LGI1 encephalitis to develop effective causative and symptomatic treatment." (PMID 39141878, 2024). "Several neural-specific autoantigens have been linked to autoimmune limbic encephalitis (LE); encephalitis related to anti-LGI-1 antibody was first reported in 2010." (PMID 39734683, 2024). "An eventual diagnosis of relapse of anti-LGI1 encephalitis was made after the exclusion of other causes." (PMID 39867015, 2024). "In a patient with LGI1 encephalitis, dementia caused an mRS score increase to 2 points irresponsive to immunotherapy." (PMID 38862652, 2024). "The axon guidance pathway, for example, was more likely to be implicated in the pathological progression of LGI1 encephalitis since it was one of the KEGG pathways enriched for elevated microRNAs." (PMID 37644514, 2023). "This patient was diagnosed with LGI-1 antibody-associated encephalitis based on electroencephalography (EEG) examinations and autoimmune encephalitis antibody analyses." (PMID 37553563, 2023). "LGI-1 antibody-associated encephalitis is a type of autoimmune encephalitis with a lower prevalence than NMDAR antibody-associated encephalitis." (PMID 37553563, 2023). "Anti-LGI1 encephalitis is strongly associated with genetic risk factors, including human leukocyte antigen (HLA) alleles DRB1*07:01 and DRB1*04:02 haplotypes in Whites and Asians, and DRB1*03:01 in Chinese anti-LGI1 cases." (PMID 37644514, 2023). "This patient was diagnosed with LGI-1 antibody-associated encephalitis through a combination of electroencephalography examinations and autoimmune encephalitis antibody analyses." (PMID 37553563, 2023). "The incidence of LGI-1 antibody-associated encephalitis is low and it occurs mostly in middle-aged and elderly patients, although it occasionally occurs in pediatric patients." (PMID 37553563, 2023). "Our findings indicate that other AE‐associated manifestations, especially anti‐LGI1 encephalitis, should be recognized." (PMID 36971194, 2023).
encephalitis (continued). "Magnetic resonance imaging (MRI) and tests on blood and cerebrospinal fluid (CSF) demonstrated encephalitis involving the right temporal lobe and caudate nucleus and associated with LGI1-antibody." (PMID 37033571, 2023). "This concept is even more outstanding when considering anti-LGI1 encephalitis, as it is rarely associated with cancer comorbidities and has for this reason a better long-term prognosis if treated rapidly." (PMID 37275973, 2023). "Leucine-rich glioma-inactivated protein 1 (LGI-1) antibody-associated encephalitis is a subtype of autoimmune encephalitis with a low incidence." (PMID 37553563, 2023). "LGI-1 antibody-associated encephalitis is the second most prevalent of all autoimmune encephalitides." (PMID 37553563, 2023). "The patient was diagnosed with LGI-1 antibody-associated encephalitis, with the presence of a tumor having been excluded based on other ancillary tests." (PMID 37553563, 2023). "According to functional MRI studies, anti-LGI-1 encephalitis was linked to significant functional network changes." (PMID 37360339, 2023). "Epileptic seizure is a common manifestation of both LGI1-antibody positive encephalitis and LGI1 mutations." (PMID 38035091, 2023). "Leucine-rich glioma inactivated (LGI1) encephalitis is an autoimmune disorder associated with antibodies against cell surface antigens, usually leading to rapidly progressive cortical and subcortical cognitive impairment, hyponatremia, and movement disorders." (PMID 37033571, 2023). "The findings of our study provided some relevant insights regarding the relapse rate and relapse-related risk factors in anti-NMDAR, anti-GABABR and anti-LGI1 encephalitis." (PMID 35757705, 2022). "Anti-LGI1 associated encephalitis has an estimated annual incidence of 0.83 per 1 million persons, and it represents the most common cause of autoimmune encephalitis of adults older than 40 years." (PMID 36591253, 2022). "Given that some unique human leukocyte antigen (HLA) subtypes appear at a high frequency, multiple recent studies have revealed that anti-LGI1 encephalitis is associated with genetic susceptibility." (PMID 35493840, 2022). "The main clinical manifestations of anti-LGI1 encephalitis are memory loss, seizures, mental behavioral abnormalities and faciobrachial dystonic seizures(FBDS)." (PMID 36685530, 2022). "In the subgroup analysis, this association was significant only in patients with anti-LGI1 encephalitis." (PMID 35281052, 2022). "Anti-leucine-rich glioma inactivated 1 (LGI1) encephalitis is an AE subtype that is infrequently associated with neoplasms and highly responsive to prompt immunotherapy treatment." (PMID 35979060, 2022). "Subgroup analysis results showed that antibody titer was associated with the likelihood of relapse in anti-LGI1 encephalitis." (PMID 35757705, 2022). "Anti-leucine-rich glioma-inactivated 1 (LGI1) encephalitis is the second most common cause of autoimmune encephalitis and is characterized by cognitive impairment, psychiatric disorders, and faciobrachial dystonic seizures." (PMID 36211373, 2022). "Univariate analysis of variables associated with relapse in anti-NMDAR, anti-GABABR and anti-LGI1 encephalitis, respectively." (PMID 35757705, 2022). "Among patients with anti-LGI1 encephalitis, there were significant associations of the development of epilepsy with the occurrence of status epilepticus (p=0.032) and a larger number of ASMs (p=0.05)." (PMID 35281052, 2022). "In subgroup analysis, we discovered that antibody titer was associated with the likelihood of relapse in anti-LGI1 encephalitis." (PMID 35757705, 2022). "In encephalitis associated with LGI1 antibody, MTL and basal ganglia hypermetabolism have been systematically described." (PMID 34837479, 2022). "Our data confirmed that 36/60 (60%) patients responded to first-line immunotherapy, and anti-LGI1 encephalitis was associated with faster recovery, possibly due to low-affinity IgG4 antibodies." (PMID 35720290, 2022).
encephalitis (continued). "The diagnosis is confirmed by finding the anti-LGI-1 antibody and after excluding other possible causes of encephalitis." (PMID 36348436, 2022). "We investigated the factors associated with unfavorable functional outcome in anti-LGI1 encephalitis, and found that patients with positive CSF LGI1 antibodies and those who relapsed had worse outcome after treatment." (PMID 34975858, 2021). "Twenty-eight were of anti-NMDA-receptor encephalitis with other cases associated with antibodies against LGi1, Caspr2, glycine receptor, DPPX, GABAB receptor, IgLON5, GFAP, and SOX1." (PMID 33692738, 2021). "Although limbic encephalitis can also be caused by CNS infections such as HSV or HHV6 encephalitis, when autoimmune in etiology the usual antibodies associated with limbic encephalitis are anti-Hu, Ma2, LGI1, GABAB, or AMPA receptor." (PMID 33935958, 2021). "Vice versa, in most patients with AE, no immunological triggers can be found and a genetic predisposition with HLA class II genes especially in anti-LGI1 encephalitis was reported." (PMID 34749759, 2021). "The occurrence of Anti-NMDAR encephalitis has been associated with virus infection and the presence of tumors, especially ovarian teratomas, while anti-LGI1 encephalitis has been associated with significant genetic predisposition." (PMID 33193049, 2020). "For instance, patients with encephalitis caused by LGI1 antibodies showed markedly impaired verbal and visuo-spatial memory as well as a significantly reduced hippocampal volume." (PMID 32824982, 2020). "Anti-LGI1 encephalitis is strongly associated with HLA class II allele DRB1*07:01, which was carried by approximately 90% of patients, as well as B*44:03 and C*07:06 in the HLA class I allele." (PMID 33396564, 2020). "Anti-LGI1 encephalitis is the main type of autoimmune LE, generally associated with rapidly progressing cognitive impairment." (PMID 33162923, 2020). "Anti-LGI1 encephalitis is difficult to diagnose, as it can cause rapidly progressive dementia, as observed in two cases in the sample." (PMID 33551968, 2020). "We found that continuous insomnia was more frequent in patients with Caspr2-Ab-associated diseases than LGI1-Ab encephalitis, which suggested that Caspr2-Ab cause more severe sleep disturbances." (PMID 32849186, 2020). "Advanced diffusion techniques such as diffusion tensor imaging, neurite orientation dispersion and density imaging, and diffusion kurtosis imaging should be implemented in future studies to investigate microstructural changes caused by anti-LGI1 encephalitis." (PMID 33510707, 2020). "Another possible mistake associated with anti-LGI1 encephalitis is the frequent confusion of faciobrachial dystonic seizures with diverse movement disorders and focal seizures." (PMID 33551968, 2020). "Changes in MTL and hippocampal volume from swelling to atrophy were observed during the follow-up, and anti-LGI1 encephalitis can be considered as a potential cause of MTL sclerosis." (PMID 33380947, 2020). "Sleep disorders are common in VGKC-Ab diseases presenting in 20–65% patients with LGI1-Ab encephalitis and 22–68% patients with Caspr2-Ab-associated diseases." (PMID 32849186, 2020). "We conducted a retrospective study to investigate sleep disturbance and polysomnography (PSG) characteristics in patients with LGI1-Ab encephalitis and Caspr2-Ab-associated diseases." (PMID 32849186, 2020). "Perhaps in anti-LGI1 encephalitis patients, the susceptibility genes played an important role in the formation of the autoimmune milieu, which was conducive to the coexistence of ADs." (PMID 31736858, 2019). "Compared with anti-NMDAR encephalitis, anti-LGI1 encephalitis seems to show a stronger genetic predisposition mediated by HLA class II alleles." (PMID 31736858, 2019). "There are about 300 reported patients with encephalitis associated with LGI1 antibodies resulting in an estimated incidence of 0.83/million." (PMID 30524441, 2018).